FOXM1 (forkhead box M1)
Diseases named in the same sentence as FOXM1 in open-access papers (continued):
Sharing a sentence is not in itself a finding about the gene and the disease.
cancer (continued). "FOXM1 is a transcription factor belonging to the conserved forkhead box (FOX) family, which has been associated with poor prognosis in several cancer types." (PMID 38806454, 2024). "To investigate the cancer cell selectivity of FOXM1 inhibitors, we utilized the immortalized (FTE) cell line FT282-C11 as non-malignant, cell of origin matched control." (PMID 38704607, 2024). "Recent findings have indicated that the transcription factor FOXM1 plays an important role in various cancer-related events, especially drug resistance." (PMID 39086352, 2024). "We evaluated the synergistic role of FOXM1 inhibitors with chemotherapy and molecular-targeted therapies for cancer treatment." (PMID 38398147, 2024). "Considering these findings, we assumed that STL001-induced FOXM1 suppression should reduce chemoresistance in any of the different etiology of cancer cells." (PMID 38697979, 2024). "Upregulation of FOXM1 has been described in many cancers, acting as a master transcriptional regulator that promotes tumor progression, metastasis, and chemoresistance." (PMID 39524141, 2024). "In a pan-cancer analysis encompassing 18,000 tumors, the expression of FOXM1 and its co-expressed transcriptional network was the strongest prognosticator of poor outcomes." (PMID 39335162, 2024). "Many malignancies are characterized by the expression of FOXM1, and it has been suggested that this upregulation of FOXM1 expression occurs early in the development of cancer." (PMID 37976368, 2024). "Recent findings have indicated the importance of FOXM1 in the modulation of chemotherapeutic resistance in many cancers." (PMID 39086352, 2024). "In contrast, ectopic ERβ1 expression decreases FOXM1 protein and mRNA expression in ERα-positive cancer cells, suggesting that ERβ1 represses ERα-dependent FOXM1 transcription." (PMID 39594778, 2024). "The essential role of FOXM1 in tumorigenesis has been established and verified in many different cancers." (PMID 38398147, 2024). "It has been shown that NPM1 interacts with the oncogenic transcription factor FOXM1 in cancer cells." (PMID 38928092, 2024). "FOXM1 has been reported to promote chemotherapy resistance in an autophagy-dependent manner in a variety of cancers." (PMID 39086352, 2024). "MYC is overregulated in three of the five datasets and is related to: 1) cellular senescence along with FOXM1; 2) proteoglycans in cancer along with ELK1; and 3) HCV infection." (PMID 39228892, 2024). "A completely new activity of FOXM1, mediated through steroid/cholesterol biosynthetic process and protein secretion in cancer cells was also detected." (PMID 38697979, 2024). "In recent years, the development of FOXM1 inhibitors has gained a significant attention as a potential strategy to disrupt the aberrant activity of FOXM1 in breast and other cancers." (PMID 38918225, 2024). "FOXM1 has been widely studied in the context of cancer due to its role in cell proliferation, cell cycle progression, apoptosis, and other cellular processes." (PMID 38886738, 2024). "Here, the capacity of STL001 as a FOXM1 inhibitor was verified in human cancer cell lines from solid tumors." (PMID 38697979, 2024). "The microenvironment-induced FOXM1 sustains stemness, and its inactivation reduces cancer stem cells survival in the omental niche and enhances their response to the PARP inhibitor Olaparib." (PMID 38806454, 2024). "FOXM1 expression is elevated in a wide range of cancer cell lines and cancer types and can be used as a biomarker for cancer diagnosis, treatment, and prognosis 179-181." (PMID 38725864, 2024). "APC-targeted proteins, such as CDC20, Securin, HURP, FOXM1, PLK1, and the Aurora kinases, accumulate in multiple unrelated cancer types and are generally associated with more aggressive disease and worse clinical outcomes." (PMID 38730707, 2024).
cancer (continued). "Ex vivo co-culture assays revealed that FOXM1 inhibited CD8+ T cell-mediated antigen-dependent killing of cancer cells." (PMID 38373993, 2024). "The delivery of miRNA‐134 via liposomes results in the downregulation of Forkhead Box M1 (FOXM1), leading to a subsequent decrease in the proliferation and survival of cancer cells." (PMID 38919334, 2024). "Downregulation of FOXM1 expression promotes DNA damage-induced cancer cell death and disrupts mitosis/cytokinesis." (PMID 37976368, 2024). "Forkhead Box M1 (FOXM1) is a master transcriptional regulator of oncogenic phenotypes in many cancers, including HGSOC, and has been identified as a potential cancer therapeutic target." (PMID 38704607, 2024). "FOXM1 promoted the proliferation, invasion and colony formation of LUAD cells, therefore FOXM1 mediated the cancer‐promoting effect of METTL1 in LUAD." (PMID 38967523, 2024). "Because chemoresistance remains a major obstacle to cancer treatment, the development of FOXM1 inhibitors is of clinical importance." (PMID 38425293, 2024). "Among the chemical inhibitors of FOXM1, thiazole antibiotics such as thiostrepton and siomycin A have been reported to induce apoptosis in human cancer cells by repressing the transcriptional activity of FOXM1." (PMID 39272919, 2024). "Research has found that MFAP2 facilitates FOXM1 expression and regulates glycolysis in oriental cancers through the FOXM1/β-catenin signaling pathway." (PMID 38822944, 2024). "Collectively, STL001 offers intriguing translational opportunities as combination therapies targeting FOXM1 activity in a variety of human cancers driven by FOXM1." (PMID 38697979, 2024). "Recent research has established a connection between elevated FOXM1 expression and unfavorable prognoses in various cancer types, including PDAC, identifying it as an oncogenic transcription factor." (PMID 39022126, 2024). "Beyond its positive regulatory role in the cell cycle, FOXM1 engages in various cancer-related functions such as cellular proliferation, migration, invasion, and resistance to drugs." (PMID 39272919, 2024). "The lead role of FOXM1 in cancer development and chemoresistance prompted new developments in the research field of FOXM1 small-molecule inhibitors (SMIs)." (PMID 38697979, 2024). "Comparison of 32 TCGA cancer types and matched normal tissues showed that FOXM1 mRNA was overexpressed in all cancer types compared to normal tissues, and that FOXM1 mRNA and protein level were highly correlated in all of these cancers." (PMID 37370117, 2023). "FOXM1 has been involved in malignant behaviors of cancer and was demonstrated to trigger aggressiveness of CRC30." (PMID 37500893, 2023). "Because of the significance of FOXM1 in cancers, upstream regulation has drawn more attention in recent years, including the exploration of its E3 ligases." (PMID 37288663, 2023). "F106 and L108 of P22 were predicted to be the key residues to maintain P22’s binding to FOXM1 C-terminus and the synthesized M1-21 mutant (M1-21mut, F106A, and L108A) lost the ability to bind to FOXM1 C-terminus or to inhibit cancer cells." (PMID 37344857, 2023). "We have also selected a FOXM1 DBD-specific single-strand DNA aptamer to inhibit FOXM1 transcriptional functions in cancer cells." (PMID 37344857, 2023). "For instance, resistance to chemotherapy and a worse mortality rate in cancer patients is strongly related to diverse FOXM1 or FOXOs protein production levels." (PMID 37626655, 2023). "Our cancer gene therapy studies of multiple cancers with adenovirus-mediated knockdown of FOXM1 expression have supported this concept." (PMID 37344857, 2023). "FOXM1 overexpression is also involved in the promotion of epithelial-to-mesenchymal transition and cancer metastasis." (PMID 37025658, 2023). "Given its multiple roles in promoting cancer progression, FOXM1 is considered a potential target for cancer therapy development." (PMID 37598210, 2023).
cancer (continued). "Fascinatingly, inhibiting FOXM1 alone is thought to be sufficient for addressing multiple cancer processes." (PMID 37626655, 2023). "FOXM1 is overexpressed in many cancers, including RMS, and the high-levels of FOXM1 are clinically associated with a worse prognosis in RMS patients." (PMID 36816948, 2023). "In general, studies on FOXM1 Apt offer new insights into the treatment of cancers and other diseases." (PMID 37736517, 2023). "In contrast to cancer cells, the knockdown of FoxM1 in IL-1 β-induced chondrocytes improved cell viability and attenuated inflammatory responses." (PMID 37908734, 2023). "Work from our group showed that FOXM1 promoted invasiveness and endocrine resistance by expanding the cancer stem-like cell population." (PMID 37370117, 2023). "An alternative, intriguing possibility behind domatinostat inhibition of FOXM1 is that lysine-specific demethylase 1 (LSD1) is involved in the inhibition of FOXM1 expression as well as in the anti-cancer activities of domatinostat." (PMID 37445993, 2023). "Consistent with this, increasing the expression of FOXM1 in human cancer cells increased their tumorigenicity in xenograft models, while RNAi-mediated knockdown of FOXM1 decreased cancer cell proliferation and suppressed tumor growth in nude mice." (PMID 37370117, 2023). "As a survival protein, FOXM1 specifically protects cancer cells from apoptosis by upregulating antiapoptotic genes." (PMID 37598210, 2023). "In OXPHOS dependent metastatic cancer cells, FOXM1 mediated Prx3 expression facilitates suppression of ROS mediated oxidative stress induced DNA damage, senescence and apoptosis." (PMID 37025658, 2023). "FOXM1 upregulation is a poor prognostic factor in many solid tumors, and its therapeutic targeting is being exploited for the reinforcement of anti-cancer strategies." (PMID 37509358, 2023). "Our results provide a deep understanding of the biological function of HMGA1 and FOXM1 in cancer cell proliferation." (PMID 37240870, 2023). "Many human diseases are associated with FOX genetic malfunction, such as cancer development (e.g., FOXA1, FOXA2, FOXC2, FOXD1, FOXE1, FOXM1, FOXO1, and FOXO3)." (PMID 37238726, 2023). "In theory, this would also provide evidence that M1-21 outperforms FOXM1 small molecule inhibitors in cancer therapy." (PMID 37344857, 2023). "It is noteworthy that despite fewer FOXM1 targets have decreased gene expression, more FOXM1 targets have increased gene expression across all 16 cancer types, which is consistent with the enhanced overall level of FOXM1 expression." (PMID 37401400, 2023). "Compared with IGF2BP3, IGF2BP1 has a more complex role in cancer, possessing both pro- and anti-cancer effects, and therefore, IGF2BP3 correlates better with cancer progression., suggesting the importance of further studies on FOXM1 regulation of IGF2BP3." (PMID 37234166, 2023). "In this study, we apply in silico protocols to screen FOXM1-targeting peptides and analyze their anti-cancer effects." (PMID 37344857, 2023). "For example, previous studies have found that FOXM1 can serve as a general target for proteasome inhibitors (PIs) in different cancer cell lines." (PMID 37821870, 2023). "A recent study demonstrated that the Hedgehog signal is responsible for TPX2 induction through the FOXM1 transcription factor in cancer cells." (PMID 36596852, 2023). "NUAK1 was required for the Akt/FOXO1/3a axis, regulating p21CIP1, p27KIP1, and FoxM1 expression and cancer cell survival upon EGFR stimulation." (PMID 38135881, 2023).
cancer (continued). "FOXM1, an important oncoprotein and promising target in other cancers, is highly overexpressed and a marker of poor survival in patient MPNSTs, but its role in driving the disease is otherwise not known." (PMID 37686402, 2023). "Multicolor immunofluorescence analysis revealed that FOXM1 was expressed more highly in cancer tissues and was accompanied by lower RNF112 expression." (PMID 37288663, 2023). "Various studies have highlighted that the alterations arise in FOXM1 during post-transcriptional and post-translational modifications, which leads to its deregulation and overexpression in cancer cells." (PMID 37081847, 2023). "FOXM1 is a fundamental transcriptional factor that is involved in the tumor invasion, metastasis, and progression of various cancers." (PMID 36829815, 2023). "The compound STL 427944, recently identified by transcriptomic network analysis, was shown to block FOXM1 activity in various cancer cells by relocating nuclear FOXM1 to the cytoplasm, followed by autophagosomal degradation." (PMID 37370117, 2023). "Utilizing the TCGA database, mRNA expression levels of HMGA1 and FOXM1 were compared between various cancers and the corresponding normal tissues." (PMID 37240870, 2023). "next, the mRNA expression level of FOXM1 in pan-cancer through TCGA and GTEx database was analyzed for checking the expression of FOXM1 in different types of cancer." (PMID 37159818, 2023). "Two structurally similar thiazole antibiotics produced by Streptomyces species, siomycin A and thiostrepton, were identified through cell-based screens as effective FOXM1 inhibitors, which had significant anti-cancer activity." (PMID 37686402, 2023). "As indicated by a recent meta-analysis, FOXM1 can be used as a significant prognosticator for the bleak clinical outcome in many cancers." (PMID 37159818, 2023). "Pearson correlation analysis displayed that expression of HMGA1 was positively correlated with that of FOXM1 in all analyzed cancer samples in TCGA databases from GEPIA (r = 0.67, p = 0)." (PMID 37240870, 2023). "Depletion of FOXM1 in cancer cell leads to chromosomal instability and regulate various oncogenic pathways leading to tumor proliferation, migration, invasion as well as DNA damage repair." (PMID 37025658, 2023). "Several small molecule compounds, including Thiostrepton, RCM, antibiotic Siomycin A, and FDI-6, can impair the growth of cancer cells by disrupting FOXM1 transcriptional activities." (PMID 37598210, 2023). "The role of FOXM1 in tumor cells is its participation in the self–renewal and proliferation of cancer stem cells through Wnt signaling, the MAPK-ERK pathway, and the PI3K-mTOR pathway." (PMID 37081847, 2023). "This review focuses on an oncogenic transcription factor, FOXM1, which is a powerful oncogene in other cancers but little studied in MPNSTs." (PMID 37686402, 2023). "This study focuses on the therapeutic targeting of FOXM1 with M1-20, with the aim of altering cancer cell phenotypes such as proliferation, migration, and apoptosis." (PMID 37598210, 2023). "Our recent study demonstrated that M1-138, a recombinant FOXM1 N-terminal domain (1-138aa) fused with a nine-arginine cell-penetrating peptide, reduced the proliferation and migration of cancer cells." (PMID 37344857, 2023). "FOXM1 is involved in DNA damage response (DDR) in cancer cells by binding to the forkhead response element region (FHRE) of DDR gene promoters and their subsequent transactivation." (PMID 37025658, 2023). "FOXM1 helps cancer cells evade growth suppressors by turning on cell-cycle regulators and anti-oxidant genes and the advancement along the EMT composition, annexation, and the evolution of pre-metastatic niches." (PMID 37626655, 2023).
cancer (continued). "FOXM1 is a spatiotemporally expressed master TF activated by aberrant KRAS signaling to drive cancer initiation, self-renewal, and proliferation." (PMID 37191407, 2023). "The inhibition of FOXM1 in cancer cells results in decreased cell proliferation and migration, impaired metastasis, and reduced drug resistance." (PMID 37835395, 2023). "RRM2 is known to regulate DNA-damage response, cancer aggressiveness, and drug resistance, and recent studies have validated FOXM1 as a RRM2-directing transcription factor." (PMID 36597126, 2023). "To further determine their biological effects in cancers, we first collected all significantly changed genes in HMGA1- or FOXM1-overexpressed samples, and made the intersection within the three cancers LUAD, LIHC and PAAD." (PMID 37240870, 2023). "Given the significant contribution of FOXM1 in tumor initiation and progression, it is regarded as an attractive target for cancer therapy." (PMID 37288663, 2023). "FOXM1 is over-expressed in most human cancers, including epithelial cancers, such as prostate adenocarcinomas, gastrointestinal cancers, non-small-cell lung cancers and high-grade ovarian cancers, and is predictive of poorer survival in breast cancer." (PMID 36831687, 2023). "Together, M1-21, as an interfering peptide of FOXM1, has potential for the anti-cancer drug development." (PMID 37344857, 2023). "By manipulating proliferative signals, HMGA1 and FOXM1 have become important molecules involved in cancer development and progression." (PMID 37240870, 2023). "In vitro, FOXM1 drives cancer cell proliferation in multiple tumor types, including liver, neuroblastoma, and prostate cancer (PCa)." (PMID 37174744, 2023). "FOXM1 is considered a potential target for anti-cancer drug development due to its multiple roles in stimulating cancer cells." (PMID 37344857, 2023). "We further analyzed and compared the protein level of HMGA1 and FOXM1 in cancer tissues and normal ones based on the immunohistochemical staining." (PMID 37240870, 2023). "As an oncoprotein, FOXM1 activates a series of key genes for cell cycle and mitosis to promote the malignant proliferation of cancer cells." (PMID 37344857, 2023). "In this study, we found that high expression of HMGA1 and FOXM1 is a common molecular event in a variety of cancers, and they have common effects on cell cycle." (PMID 37240870, 2023). "Studies have shown that upregulation of ALKBH5 in cancer cells can enhance the translation efficiency of FOXM1 mRNA, leading to increased FOXM1 protein expression and promoting the proliferation and invasion of cancer cells." (PMID 38094306, 2023). "In tumor cells, the expression and the transcriptional activity of FOXM1 are typically upregulated, and overexpression of FOXM1 has been involved in almost all major hallmarks of cancer, manifesting an oncogenic function." (PMID 37234166, 2023). "FOXM1 Apt is a potent therapeutic agent via its capacity to efficiently hinder cancer cell proliferation by its attachment to FOXM1 protein and suppression of transcriptional activities of this protein." (PMID 37736517, 2023). "FOXM1 has been recognized as a powerful oncogene and was named the molecule of the year in 2010 for its promise as a cancer therapeutic target." (PMID 37686402, 2023). "FOXM1 is a forkhead transcription factor involved in proliferation, metastasis, and drug resistance in cancer." (PMID 38264570, 2023). "The clinical implications of multiple members of the cyclin family of proteins and the cell cycle regulator FOXM1 across multiple cancer types suggest that differences in cell cycle regulation are associated with survival disparities." (PMID 37345032, 2023). "Studies have shown that by binding FOXM1 Apt to its target and suppressing the FOXM1 protein, tumor cells can be vulnerable to death, and the growth of cancer cells is reduced." (PMID 37736517, 2023).